XCL1 (X-C motif chemokine ligand 1)
Diseases named in the same sentence as XCL1 in open-access papers (continued):
Sharing a sentence is not in itself a finding about the gene and the disease.
tumor (continued). "When normalized by the tumor volume, mice vaccinated with the Xcl1 fusion proteins also showed higher numbers of OVA-specific CD8+ T cells, as compared to cohorts vaccinated with free OVA SLP + CpG, with or without free Xcl1." (PMID 30863405, 2019).
cancer (41 papers, 2014 to 2025). A tumor composed of atypical neoplastic, often pleomorphic cells that invade other tissues. "We first utilised the Cancer Cell Line Encyclopaedia (CCLE) RNA-seq data to analyse the association of XCL1/2 with ESCC." (PMID 39419971, 2024). "Matsuo and coworkers sought to develop a cancer vaccine using XCL1 as an adjuvant but had limited success until they used an XCL1 variant locked in the GPCR-binding fold by an additional a disulfide bond." (PMID 35561475, 2022). "The XCL1-Glypican-3 fusion gene has been developed as a cancer vaccine, showing promise in enhancing the generation of GPC3-specific CD8+ T cells, delaying liver cancer growth and improving the efficacy of anti-PD-1 therapy." (PMID 41426973, 2025). "Recent studies have also demonstrated the importance of XCL1/XCR1 in cancer cell proliferation, migration, and invasion." (PMID 33377624, 2021). "On the other hand, we considered using XCL1 itself as an adjuvant to attract XCR1-expressing cDC1s into the injection site of cancer vaccines for efficient antigen delivery to cDC1s." (PMID 34885241, 2021). "Here we focus on the recent progress in DC-based cancer vaccines and especially the use of the XCR1 and its ligand XCL1 axis for the targeted delivery of cancer vaccines to cross-presenting dendritic cells." (PMID 34065346, 2021). "Among these strategies, only cancer cells genetically engineered to express XCL1, and thus to attract cDC1, have been tested or are being currently evaluated in ongoing clinical trials." (PMID 32075343, 2020). "Next, we investigated if the activation of ERK/HIF-1α/EMT signaling was also involved in the migration of the other types of cancer cells, such as A549 and Panc1 cells treated with XCL1." (PMID 33374849, 2020). "The mechanism of XCL1 in cancer progression and its role in cancer prognosis should be examined further in future investigations." (PMID 31991604, 2020). "Among the differentially expressed IRGs, we identified 5 IRGs (CD1B, XCL1, PLCG2, NGF, and OXTR) for inclusion in the risk score, and previous studies have indicated that these genes were related to immune processes and cancer progression." (PMID 32508884, 2020). "Given that cancer vaccines are ultimately evaluated for their capacity to protect against tumors, the Xcl1 fusion proteins were tested in therapeutic settings against the OVA-expressing EL-4 lymphoma model (EG7)." (PMID 30863405, 2019). "Existing reports on XCL1 have shown its potent roles in the occurrence and development of carcinomas, mycobacterium tuberculosis infection, HIV infection, allergic inflammation and nerve injury." (PMID 29141038, 2017). "Interestingly, EC cell lines had the highest level of XCL1 mRNA expression out of all cancer types profiled." (PMID 39419971, 2024). "In the near future, a combination therapy of immune checkpoint inhibitors and cancer vaccines based on molecules such as the stable and highly active form of XCL1 may greatly improve the efficacy of cancer immunotherapy." (PMID 34065346, 2021). "On the basis of these findings, we have proposed that a stable and highly active form of XCL1 could be used as a new adjuvant selectively activating cDC1s and also as a fusion partner of cancer antigens for cDC1-targeted cancer vaccines." (PMID 34065346, 2021). "In contrast, CCL14 and XCL1 only serve as good prognostic factors for cancer patient outcomes." (PMID 31991604, 2020). "XCL1 (log2(FC) = 1.33, FDR = 8.71e-05) and SRPX2 (log2(FC) = 1.45, FDR = 0.0002) have been reported to enhance cancer progression and promote cancer migration, the up-regulation of which was mainly caused by de-methylation in the stage IV cancer." (PMID 25648588, 2014). "Interestingly, the efficacy of the Xcl1-Fc to promote effective targeting of the synthetic long peptide immunogen as a mixture might greatly facilitate the formulation of cancer type-specific, and neo-antigen therapeutic vaccines." (PMID 30863405, 2019).
cancer (continued). "We have shown that the stable form of XCL1 is highly chemotactic and efficiently induces antigen-specific CTL responses by attracting cDC1s when co-injected with cancer vaccines." (PMID 34885241, 2021). "In human cancers, intra-tumoral CCL5, XCL1, and XCL2 transcripts closely correlate with NK cells/cDC1 gene signatures and are associated with increased overall patient survival in several cancer types." (PMID 32218226, 2020). "While CCL2, CXCL10, and CX3CL1/CX3CR1 can serve as favorable or unfavorable prognostic factors depending on the cancer types, CCL14 and XCL1 possess good prognostic value." (PMID 31991604, 2020). "In particular, the CC-chemokine ligand 5, XC-chemokine ligand 1 (XCL1) and XCL2, which results in enhanced recruitment of dendritic cells (DCs) into solid tumors and subsequent improved survival in cancer patients." (PMID 30871206, 2019). "By the way, there is no consistent phenomenon of X-C Motif Chemokine Ligand 1/2 (XCL1/2) in pan-cancer gene expression or patient survival prognosis." (PMID 37895310, 2023). "CCL5, XCL1, XCL2, CCL17, CCL22, and CCL19 showed a positive correlation with DEF6 in most cancers, and DEF6 may function in regulating these chemokines in cancer." (PMID 36686789, 2022). "While CCL14 and XCL1 have shown only good prognostic value, other chemokines such as CCL5, CCL20/CCR6, CCR7, CXCL1, CXCL8, and CXCL12/CXCR4 have consistently played the role of poor prognostic markers in different kinds of cancer." (PMID 31991604, 2020). "In contrast, however, activation of the ERK/HIF-1α/EMT signaling was not induced by XCL1 in the other types of cancer cells such as A549 and Panc1 cells." (PMID 33374849, 2020). "Among the remaining 8 DEGs (ADRA2A, P2RX6, XCL2, XCL1, CCL7, TRIM54, TNFRSF18 and SPOCK1), the expression of ADRA2A, the top one, in KIRC based on individual cancer is lower than the normal tissues, but patients with lower expressed ADRA2A have a better overall survival (OS)." (PMID 31159832, 2019). "Altogether, these results demonstrate that therapeutic cancer vaccines may be greatly improved by the combination of SLP antigen and Xcl1 fusion proteins." (PMID 30863405, 2019). "Similarly, in human cancers, intratumoral CCL5, XCL1, and XCL2 transcripts closely correlate with gene signatures of both NK cells and cDC1 and are associated with increased overall patient survival." (PMID 29429633, 2018). "Therefore, although MMP-2 and -9 participate in the signaling pathway related to cell migration and invasion induced by XCL1 in various cancer cell types, these MMPs do not appear to contribute to the XCL1-induced promotion of MDA-MB-231 cell migration." (PMID 33374849, 2020). "Thus, a stable form of XCL1 may be a highly promising adjuvant for the induction of effector and memory CD8+ T cells in the prevention and treatment of infectious diseases and cancer." (PMID 30542351, 2018).
infection (27 papers, 2010 to 2024). The state of being infected such as from the introduction of a foreign agent such as serum, vaccine, antigenic substance or organism. "Both Xcl1-HA- and fliC-HA-immunized mice were protected from challenge and only displayed moderate weight loss during the infection." (PMID 35296089, 2022). "Both Xcl1(Δ1)-HA and Xcl1-HA induced full protection and minimal weight loss during the course of the infection." (PMID 31156636, 2019). "To evaluate a more long-term protection, we challenged mice 12 weeks after a single immunization and observed that while the protection afforded by WT Xcl1 targeting had waned by this time point, displaying weight loss after infection, Xcl1(Δ1) targeting still provided complete protection." (PMID 31156636, 2019). "Chemokines (CCL2, CCL3L1, CCL4, CXCL9, CXCL10, CXCL11, and XCL1) were also significantly upregulated after infection." (PMID 38698849, 2024). "These were accompanied by activation of genes related to cytokine production, including TGFB, CXCL6, TNFSF15 and XCL1, which prompt the recruitment of immune cells to the location of an ongoing infection." (PMID 36178892, 2022). "It is the receptor for chemokine XCL1, which is produced in response to infection and inflammation, and during development of regulatory T cells." (PMID 34616619, 2021). "Following infection, only XCL1 and CCL7 mRNAs were significantly increased in the spleen of WT mice on day 3 postinfection, which declined to the mock-infected levels on day 7 postinfection and remained low at day 35 postinfection." (PMID 32310998, 2020). "We are not aware of any data in the literature on the capacity of elite controllers during early infection to express higher levels of XCL1." (PMID 28350860, 2017). "Here, we provide evidence that PBMCs from elite controllers during early infection produce higher mRNA levels of XCL1 than PBMCs from uninfected subjects." (PMID 28350860, 2017). "Increased accumulation of the chemokines chemokine (C motif) ligand 1 (Xcl1), chemokine (C-C motif) ligand 5 (Ccl5), and chemokine (C-C motif) ligand 19 (Ccl19) have been observed in infection." (PMID 28075380, 2017). "The elite controllers expressed unique transcripts early in infection that were closely associated with specialized cross-presentation between XCR1+ DCs and antigen-specific CD8+ T cells (XCL1)." (PMID 28350860, 2017). "The more complete HA constructs offered modest protection with αMHCII:HA-immunized animals recovering slightly faster than the naive animals, and the XCL1:HA-immunized animals gaining weight on d7 post infection." (PMID 27602032, 2016). "HIV-1 inhibition by XCL1 was shown to occur at an early stage of infection, via blockade of viral attachment and entry into host cells." (PMID 24385911, 2013). "To further examine the breadth of XCL1-mediated inhibition, we evaluated the ability of recombinant XCL1 to inhibit infection of primary PBMC with a panel of primary HIV-1 isolates with different coreceptor-usage specificity." (PMID 24385911, 2013). "IEC isolated from neonates at the peak of the infection presented a clear up-regulation of XCL1, CCL3, CCL4, CCL5, CXCL9, and CXCL10 expression, with levels close to those in adults for CXCL9 and CXCL10." (PMID 24367259, 2013). "Consequently, the antibodies induced after one immunization with Xcl1-HA or fliC-HA were sufficient to protect against infection." (PMID 35296089, 2022). "In this regard, we suggest that our observation of upregulated XCL1 only in elite controllers during early infection might indicate communication between cross-presenting XCR1+DCs and antigen-specific CD8+ T cells that should be investigated in future studies." (PMID 28350860, 2017). "Indeed, we documented XCL1-mediated blockade of HIV-1 at an early stage of infection, namely, viral attachment and entry." (PMID 24385911, 2013).
infection (continued). "In our model, some chemokines reported to be part of the "1st and 2nd waves" of chemokine expression by DC cells, specifically Xcl1, Cxcl9, Cxcl16, Ccl1, Ccl2, Ccl3, Ccl4, Ccl5, Ccl7 and Ccl8 are expressed at increased levels in lung i.n. samples at 3 weeks post-infection." (PMID 20942964, 2010). "Thus, XCL1 release from cluster 3 DETCs responding to episodic, low-level KC dysregulation might, in cases of infection or genotoxicity, facilitate neoantigen uptake by DCs, thereby initiating cytotoxic CD8+ T cell immunosurveillance." (PMID 35165446, 2022). "The expressions of MIF, XCL1 and CXCL12 decreased at the early stage of infection, indicating IBV affects macrophage chemotaxis." (PMID 33509253, 2021). "DC isolated early after infection of pigs with either of the two CSFV strains showed prominent upregulation of CCL5, CXCL9, CXCL10, CXCL11, and XCL1, as well as of the cytokines TNFSF13B, IL6, IL7, IL12B, IL15, IL27." (PMID 32733474, 2020). "The chemokines XCL1 and CCL3 (also known as MIP-1α) induce immune responses against pathogen infection." (PMID 25313504, 2014). "Indeed, early studies have suggested that Xcl1 functions in concert with IFNγ, MIP1α, MIP1β, and RANTES in promoting Th1 responses after infection." (PMID 35296089, 2022). "As an additional test for specificity of the interaction between XCL1 and the HIV-1 envelope glycoprotein (gp120), we performed both virion-capture and infection assays using VSV-G pseudotyped virions, which contain an HIV-1 core surrounded by the VSV envelope." (PMID 24385911, 2013). "4-1BB ligation did not induce production of IL-4, a Th2 cytokine, IL-17, a cytokine which contribute to protection to MTB challenge and XCL-1, a chemokine released by suppressor CD8+ T cells during the chronic stage of infection with MTB that negatively affects production of IFN-γ by CD4+ T cells." (PMID 20544034, 2010). "We found that the expression of CX3C subfamily (CX3CL1) and the C subfamily member (XCL1) was only highly increased in the H9N2-infected mice compared to the mock control, but the expression of CCL4, CXCL1, and CXCL2 was significantly increased in both single infection groups." (PMID 33968006, 2021). "Although there was a modest increase of XCL1, CCL2, CXCL2 and CXCL10 mRNAs in these mice following infection, this was not statistically significant." (PMID 32310998, 2020).
intestinal disease (1 paper, 2022). "Together, these results indicate that intestinal disease-associated Tc17 cells represent a distinct population of inflammatory CD8+ T cells prone to co-produce TNF that can be further functionally subdivided into three subpopulations based on IFN-γ, IL-22 and XCL-1 production." (PMID 35760777, 2022).
XCL1 also shares sentences with these, for which no sentence is quoted: COVID-19 (3 papers); gastric cancer (3); lung adenocarcinoma (3); Autoimmunity (2); Granuloma (2); head and neck squamous cell carcinoma (2); adenocarcinoma (1); adenosquamous carcinoma (1); autoimmune disease (1); brain disease (1); breast invasive carcinoma (1); coccidiosis (1); colon adenocarcinoma (1); colorectal adenocarcinoma (1); colorectal cancer (1); Cornelia de Lange syndrome (1); cystic teratoma (1); diabetic neuropathy (1); emphysema (1); experimental autoimmune encephalomyelitis (1); glioblastoma (1); glioma (1); heart failure (1); holoprosencephaly (1); infectious disease (1); Insulin resistance (1); intestinal tumor (1); joint diseases (1); leukemia (1); liver disease (1).
A further 16 diseases each share a sentence with XCL1 in 1 paper.